HPSE (heparanase)
Diseases named in the same sentence as HPSE in open-access papers (continued):
Sharing a sentence is not in itself a finding about the gene and the disease.
diabetes (continued). "However, the induction of diabetes was also observed in 100% of HPSE-1-deficient RIP-OVAhi recipient mice that received WT OT T cells, despite a significant difference in exocrine tissue histology between WT and HPSE-1-deficient RIP-OVAhi mice (p = 0.008, Score 5, WT versus HPSE-1-deficient hosts)." (PMID 40362360, 2025). "Notably, heparanase was implicated in diabetes and its complications." (PMID 31921662, 2019). "Moreover, taken together with the well-established causal role of the enzyme in PDAC progression, our findings indicate that heparanase may sustain (at least in part) reciprocal causality between diabetes and pancreatic tumorigenesis." (PMID 31921662, 2019). "Given the fact that heparanase impairs surface glycocalyx in glomerular endothelial cells, these findings suggest that NO deficiency may upregulate heparanase expression in glomerulus in the setting of diabetes, disrupting the endothelial surface glycocalyx, and lead to albuminuria." (PMID 25371905, 2014). "Thus, therapeutic inhibition and prevention of microvascular diseases associated with diabetes could be addressed using apoEdp to inhibit heparanase activation." (PMID 23284911, 2012). "Heparanase therefore represents a new therapeutic target for suppressing atherosclerotic cardiovascular disease in people with diabetes." (PMID 42290526, 2026). "This study demonstrates that heparanase is a prominent pro-inflammatory protein driving the diabetes-accelerated formation of advanced atherosclerotic lesions with an unstable phenotype." (PMID 42290526, 2026). "In summary, our molecular studies using the RIP-OVAhi mouse model of diabetes induction emphasize that the cellular source of HPSE-1 is site-specific." (PMID 40362360, 2025). "Using this acute model for inducing diabetes, we confirmed our previous discovery of a major role for the heparan sulfate (HS)-degrading enzyme HPSE-1 in islet inflammation and immune-mediated damage of insulin-producing beta cells." (PMID 40362360, 2025). "Nevertheless, our study has revealed an important role for HPSE-1 in pancreatic exocrine inflammation during diabetes development." (PMID 40362360, 2025). "In contrast to inflammation, HPSE-1 expressed by donor T cells played a key role in the induction of diabetes by allowing autoimmune T cells to traverse peri-islet BMs in order to destroy insulin-producing beta cells." (PMID 40362360, 2025). "Patients with type 2 diabetes mellitus (T2DM) are known to have increased levels of HPSE activity, and it is well known that HPSE is essential for the development of diabetic nephropathy." (PMID 36889064, 2023). "In fact, the involvement of heparanase in diabetes and its complications was actively investigated during the last decade." (PMID 38078007, 2023). "Here we report that in the context of hyperinsulinemic conditions [a common phenomenon in PDAC, either in the setting of new onset or long-standing diabetes], heparanase augments insulin-INSR signaling cascade in pancreatic tumor cells." (PMID 38078007, 2023). "Consistent with our observations, two recent studies reported that heparanase protected hpa-TG mice from streptozotocin-induced diabetes and attenuated heart injury from ischemia/reperfusion or toxic insults." (PMID 36293542, 2022). "Subsequent studies with HPSE-1-deficient OT-II and OT-I T cells demonstrated, as expected, that antigen-activated CD4+ OT-II T cells are the dominant T cell population involved in diabetes induction." (PMID 35563015, 2022). "Here, applying mouse model of metabolic syndrome/diabetes and concurrent pancreatic carcinoma, we show that diabetic state leads to induction of heparanase expression in PDAC." (PMID 31921662, 2019). "Previous study demonstrated an increase of heparanase levels in diabetes patients, which can be detected in urine and plasma of the patients." (PMID 31890010, 2019).
diabetes (continued). "Significantly, treatment of NOD mice with the heparanase inhibitor/HS replacer PI-88, reduced the incidence of diabetes by ~50% and preserved intra-islet HS." (PMID 29415062, 2018). "Noteworthy, reports by Parish and co-workers also suggested a role for heparanase in the pathogenesis of diabetes per se." (PMID 28038446, 2017). "Heparanase, an endoglycosidase that cleaves heparan sulfate, is involved in extracellular matrix turnover, inflammation, kidney dysfunction, diabetes, fibrosis, angiogenesis and cancer progression." (PMID 28388547, 2017). "Further, heparanase is upregulated in numerous human diseases such as cancer, diabetes, renal disease, and Alzheimer disease." (PMID 27416066, 2016). "Overexpression of heparanase in diabetic mouse models increased TNF-α expression in kidney tissue and activated kidney-damaging macrophages, whereas heparanase knockout mice with diabetes demonstrated reduced albuminuria." (PMID 26064987, 2015). "Diabetes and vascular injury increase the expression of heparanase and transgenic mice with overexpression of heparanase increase thrombosis after mild vascular injury." (PMID 24147020, 2013). "In contrast, kidney transplantation did not restore urinary heparanase in our cohort, suggesting that heparanase is derived from distinct cell populations in diabetes and CKD conditions." (PMID 23028487, 2012). "A loss of GBM and tubular HS was noted in kidney biopsies from patients with overt diabetes, accompanied by increased expression of heparanase." (PMID 23028487, 2012). "In diabetes, urine heparanase correlated with blood glucose levels, suggesting that glucose is involved in heparanase regulation." (PMID 23028487, 2012). "This is in agreement with previous publications demonstrating increased heparanase activity and protein levels in the urine of a small group of diabetes patients." (PMID 21364956, 2011). "Here, we examined heparanase levels in the plasma and urine of patients with type 2 diabetes mellitus (T2DM), T2DM patients who underwent kidney transplantation and control healthy volunteers." (PMID 21364956, 2011). "Of increasing importance is the apparent role of heparanase in diabetes and related complications, primarily diabetic nephropathy." (PMID 21364956, 2011). "Emerging evidence indicate that heparanase is also engaged in diabetes and related complications, primarily kidney dysfunction." (PMID 21364956, 2011). "Heparanase, the sole enzyme responsible for cleaving heparan sulfates in the endothelial glycocalyx and subendothelial extracellular matrix, plays important pro-inflammatory roles in diabetes and atherosclerosis." (PMID 42290526, 2026). "Protecting the endothelial glycocalyx damage in diabetes, using the novel heparanase inhibitor OVZ/HS-1638, effectively prevents microvascular permeability changes associated with DR and DKD, demonstrating a novel systemic approach to address diabetic microvascular complications." (PMID 38302978, 2024). "We next investigated the impact of eGlx damage in diabetes and determined whether treatment with the heparanase inhibitor OVZ/HS-1638 could prevent systemic eGlx damage and the associated permeability increases in a T2D mouse model using db/db mice." (PMID 38302978, 2024). "Although the matrix metalloprotease (MMP) enzyme family can cleave HS proteoglycan core proteins found in the eGlx such as Syndecan-4, heparanase-1 is the only known mammalian endoglycosidase with the capability to directly cleave HS, and is systemically upregulated in diabetes." (PMID 38302978, 2024). "Thus, one of the strategies to treat diabetes is to inhibit the multistep impairment of heparanase to the HS of pancreatic islets and β-cells, which is one of the factors in the development of diabetes." (PMID 36292936, 2022).
diabetes (continued). "Heparanase 1 (HPSE1), the only known endo-β-d-glucuronidase capable of degrading heparan sulfate chains in mammals, was upregulated in many inflammatory diseases including cancer, diabetes, and atherosclerosis." (PMID 35185540, 2021). "We also confirmed heparanase expression in diabetic mellitus model in rats." (PMID 31890010, 2019). "Third, post-treatment of HXSF ameliorated the diabetes-elevated ROS, inflammatory cytokines and glomerular hyper-filtration, companied with lower levels of arginase activity, arginase 2 and heparanase expression and levels of HS expression in glomerular region." (PMID 30319431, 2018). "Similarly, Gil and colleagues demonstrated that heparanase null mice fail to develop albuminuria and renal damage in response to streptozotocin-induced diabetes mellitus." (PMID 28388547, 2017). "Understanding how heparanase works may lead to a valuable medical breakthrough related to diabetes, angiogenesis, cancer, and many inflammatory conditions." (PMID 23284911, 2012). "It should be kept in mind that transplanted patients are treated with immunosuppressive drugs, in addition to diabetes-related medication, which may affect heparanase secretion." (PMID 21364956, 2011). "Utilizing an ELISA method capable of detection and quantification of heparanase, we examined heparanase levels in the plasma and urine of a cohort of 29 patients diagnosed with type 2 diabetes mellitus (T2DM), 14 T2DM patients who underwent kidney transplantation, and 47 healthy volunteers." (PMID 21364956, 2011). "The results imply that heparanase is engaged in diabetes and related complications and, thus, may serve as a diagnostic marker and drug target for T2DM." (PMID 21364956, 2011). "Importantly, elevated levels of heparanase were also found in the plasma of diabetes patients, ultimately leading to systemic spread of heparanase, possibly affecting distant organs, tissues and cells." (PMID 21364956, 2011). "We hypothesised that eGlx HS plays a key role in the barrier properties of retinal and glomerular capillaries and that inhibiting heparanase to protect eGlx HS, could serve as a novel systemic approach to protect against microvascular complications in diabetes." (PMID 38302978, 2024). "While the diabetes-promoting action of PDAC is explained by several studies as a paraneoplastic phenomenon caused by specific PDAC-secreted mediators, our present findings provide an explanation for the PDAC-promoting action of diabetes, emphasizing the role of heparanase." (PMID 38078007, 2023). "PI-88, OGT2115, and heparinoids (functional HS) are candidates for diabetes drugs targeting HS because they have HS-like structures and maintain the functions of pancreatic islets and β-cells by compensating for an impaired HS function or by inhibiting heparanase." (PMID 36292936, 2022). "Previously reported inducibility of heparanase gene by diabetic milieu components in several non-cancerous cell types prompted us to hypothesize that in the setting of diabetes-associated PDAC, hyperglycemic state may induce heparanase overexpression." (PMID 31921662, 2019). "Moreover, taken together with the previously demonstrated causal role of the enzyme in PDAC progression, our observations indicate that heparanase may be a part of the bi-directional link between diabetes and pancreatic tumorigenesis." (PMID 31921662, 2019). "However, the role of heparanase in diabetes-accelerated atherosclerosis is unknown." (PMID 42290526, 2026). "We previously reported that HPSE-1 expression in both donor OT T cells and recipient RIP-OVAhi mice significantly contributes to the development of diabetes." (PMID 40362360, 2025). "Likewise, we suggest that the local production of HPSE-1 by host innate immune cells, e.g., neutrophils and platelets, that can accompany T cells during diabetes pathogenesis could disrupt the BM of acini, possibly leading to the apoptosis of acinar cells via anoikis." (PMID 40362360, 2025).
diabetes (continued). "We next wanted to dissect the separate roles of HPSE-1 in antigen-specific CD4+ and CD8+ T cells in the process of islet infiltration and diabetes pathogenesis." (PMID 35563015, 2022). "The results showed that WT OT-II T cells caused 60–70% diabetes incidence, regardless of whether or not the OT-I T cells expressed HPSE-1; by contrast, deficient OT-II T cells only induced diabetes in 20% of recipient mice, even when accompanied by WT OT-I T cells." (PMID 35563015, 2022). "Here, utilizing a mouse model of diet-induced metabolic syndrome/diabetes, we found accelerated PDAC progression in hyperglycemic mice, occurring along with induction of heparanase in PDAC." (PMID 31921662, 2019). "Heparanase treatment in a donor stem cell transplant model is reported to reduce rejection, improve cell survival and reduce TH2 responses and prevent diabetes in mice." (PMID 30194334, 2018). "Renal heparanase, mainly in podocytes is abnormally up-regulated by high glucose, ROS and renin-angiotensin system (RAS) in diabetes condition." (PMID 28743882, 2017). "In contrast, HPSE-1 deployed mainly by donor diabetogenic T cells results in islet entry, beta cell destruction (due directly to HPSE-1 as well as other damaging immune mechanisms), and ultimately in diabetes onset." (PMID 40362360, 2025). "Importantly, our data provided further evidence that protection of the eGlx using a novel class of heparanase inhibitors OVZ/HS-1638, is an effective systemic approach to protect against the microvascular complications in diabetes." (PMID 38302978, 2024). "We will also study the effect of our lead compounds on other pathological indications involving heparanase, such as chronic inflammation (i.e., colitis, pancreatitis), tissue fibrosis, kidney dysfunction (i.e., AKI, diabetic nephropathy), and diabetes." (PMID 34199150, 2021). "As this effect was also duplicated by active heparanase, high glucose, together with its secretion of heparanase, could be the unforeseen mechanism by which the EC can increase its expression of GPIHBP1 to augment the supply of FAs following diabetes." (PMID 34356640, 2021). "While heparanase deficiency did not affect blood glucose or serum lipid levels, it significantly reduced the diabetes-dependent increase in circulating MCP-1 levels and diabetes-accelerated development of atherosclerotic lesions in the aortic sinus and aorta." (PMID 42290526, 2026). "However, remarkably, the absence of HPSE-1 in both donor T cells and recipient mice resulted in a dramatic and highly significant increase in the frequency of diabetes-free mice from 0% in WT to ~60% in double KO mice." (PMID 35563015, 2022). "Although HPSE-1 from antigen-specific CD4+ T cells is clearly involved in diabetes initiation, it did not attain the diabetes incidence observed in WT controls." (PMID 35563015, 2022).
diabetic nephropathy (40 papers, 2009 to 2025). "Upregulation of HPSE associated with pathological processes has been widely described, including tumors, inflammatory bowel disease, rheumatoid arthritis, diabetic nephropathy, or atherosclerosis." (PMID 29379222, 2017). "Heparanase-1, an endoglycosidase that cleaves heparan sulfate, is implicated in the pathogenesis of diabetic nephropathy and is necessary to FGF-2 for the induction of tubular cells transition." (PMID 23095131, 2012). "Notably, we recently showed that HPSE is essential for the development of proteinuria and renal damage in experimental glomerulonephritis and diabetic nephropathy, since HPSE-deficient mice displayed reduced proteinuria compared to wild-type mice." (PMID 37475889, 2023). "Heparanase-induced glycocalyx degradation leads to albuminuria and increased glomerular heparanase expression was shown to be associated with the development of diabetic nephropathy in humans and mice." (PMID 28103268, 2017). "In addition, heparanase mRNA expression correlated with increased serum creatinine levels and a reduced glomerular filtration rate (GFR), in accordance with studies on the causal involvement of heparanase in the development of diabetic nephropathy." (PMID 29226146, 2017). "This hypothesis is supported by evidence from animal experimental models and clinical observations, which show increased heparanase levels associated with HS loss in various proteinuric diseases, including diabetic nephropathy, MCD, IgA nephropathy, lupus nephritis, and membranous nephropathy." (PMID 40495439, 2025). "Heparanase degrades heparan sulfate glycosaminoglycans, a key component of the glycocalyx, and is upregulated in renal epithelial cells in experimental diabetic nephropathy." (PMID 38271614, 2024). "HPSE has been shown to be essential for the development of diabetic nephropathy, and type 2 diabetes patients show increased levels of HPSE activity." (PMID 36889064, 2023). "In humans, studies demonstrated that serum and urinary heparanase levels were markedly elevated in type 2 diabetes patients compared to health controls and were essential for the development of diabetic nephropathy." (PMID 35769078, 2022). "An additional layer of evidence as to the involvement of heparanase in diabetic nephropathy is its levels observed in the urine of diabetic patients." (PMID 33804258, 2021). "Glycocalyx degradation is a crucial step for inflammatory cell recruitment, and heparanase is necessary for macrophage infiltration in diabetic nephropathy and I/R injury." (PMID 33804258, 2021). "Although heparanase is recognized for its important role in diabetic nephropathy and other progressive CKD, its direct involvement and mode of action in the pathogenesis of AKI has not been studied thoroughly." (PMID 28388547, 2017). "In particular locally active heparanase plays a critical role in the development of diabetic nephropathy in mice." (PMID 28103268, 2017). "Several recent findings indicate that HPSE is involved in the pathogenesis of renal fibrosis in proteinuric disease such as diabetic nephropathy." (PMID 27467172, 2016). "A role for HPSE has been identified in several proteinuric nephropathies mainly in the pathogenesis of diabetic nephropathy (DN) and in a model of septic AKI." (PMID 27467172, 2016). "Increased urine and plasma levels of HPSE have been, also, reported in patients affected by a number of renal diseases (mainly diabetic nephropathy)." (PMID 26040666, 2015). "Heparanase-1 activation, albuminuria, and a decrease in glomerular heparan sulfate (HS) have been described in diabetic nephropathy (DN)." (PMID 25192337, 2014). "Expression of heparanase is up-regulated in the course of diabetic nephropathy and other kidney diseases, possibly destructing the permselective properties of HS." (PMID 21364956, 2011).